ANGPT2 (angiopoietin 2)
Diseases named in the same sentence as ANGPT2 in open-access papers (continued):
Sharing a sentence is not in itself a finding about the gene and the disease.
malaria (continued). "Low angiopoietin-1 and high angiopoietin-2 plasma level are associated with retinopathy, discriminate human CM and severe non-cerebral malaria from uncomplicated malaria, and predict mortality from human CM." (PMID 23630573, 2013). "Malaria related mortality is associated with significant deregulation of host inflammatory factors such as interferon-inducible protein 10, a member of the CXC or α-subfamily (CXCL10), and host angiogenic factors such as angiopoietin 1 (Ang-1) and angiopoietin 2 (Ang-2)." (PMID 35836234, 2022). "Some biomarkers (C-reactive protein, angiopoietin 2, angiopoietin-2/1 ratio, platelet count, histidine-rich protein 2) have yielded interesting results in the prognosis of Plasmodium falciparum severe malaria, but for severe P. vivax and P. knowlesi malaria, similar evidence is missing." (PMID 36036460, 2022). "Changes in sTNFR1, Angpt-2, and Angpt-1 were all evident in severe malaria-associated AKI and future studies are warranted to evaluate whether polymorphisms in the ANGPT2 gene may also modify the risk of AKI severity and recovery in the context of severe malaria." (PMID 35456111, 2022). "Therefore, since Angiopoietin-1 and angiopoietin-2 are critical regulators of endothelial activation and integrity, their levels in serum samples of malaria subjects may help to discriminate between severe and uncomplicated malaria." (PMID 32565839, 2020). "Therefore, the study sets are established to evaluate the levels of serum angiopoietin-1 and angiopoietin-2 with some hematological parameters (total white blood cell counts, total red blood cell counts, platelet counts, and malaria parasite density) in malaria-infected children." (PMID 32565839, 2020). "In addition, WPBs also store and release angiopoietin-2 (Ang-2), an autocrine mediator of endothelial activation that is associated with mortality and endothelial dysfunction in severe falciparum malaria, and with AKI in knowlesi malaria." (PMID 29690924, 2018). "In addition, we now show that in knowlesi malaria, intravascular haemolysis is independently associated with the endothelial cell WPB constituents angiopoietin-2 and OPG, suggesting that endothelial activation is likely a key mediator of haemolysis-induced end-organ damage." (PMID 29872039, 2018). "Both angiopoietin-2 and OPG correlated with age in knowlesi malaria patients (r = 0.39, p < 0.0001, and r = 0.43, p < 0.0001, respectively), independent of parasitaemia." (PMID 29872039, 2018). "In both Gambian and Tanzanian children with severe malaria, ADMA was correlated with biomarkers of endothelial activation (sVCAM and Angiopoietin-2, respectively)." (PMID 26407009, 2015). "Using logistic regression analysis, we explored the relationships between plasma angiopoietin-2 levels, parasite VSA expression and the two syndromes of severe malaria, impaired consciousness and respiratory distress." (PMID 24674301, 2014). "We tested relationships between plasma arginase activity, plasma sCD163, and plasma IL-10 with selected parameters of malaria disease activity and NO-related measures—HRP-2, angiopoietin-2, plasma lactate, plasma arginine, the arginine/ADMA ratio, blood hemoglobin, and blood platelets." (PMID 27385484, 2016). "Beside sequestration of IE, severe malaria is characterised by systemic endothelial activation and widespread release of activation markers such as von Willebrand factor (vWF), soluble ICAM-1(sICAM-1) and angiopoietin-2 (ang-2)." (PMID 24674301, 2014). "We therefore measured CFHb in Malaysian adults with severe and non-severe knowlesi malaria, and assessed associations with the endothelial WPB constituents angiopoietin-2 and osteoprotegerin, endothelial and microvascular function, and other markers of disease severity." (PMID 29872039, 2018).
gastric cancer (25 papers, 2010 to 2025). A primary or metastatic malignant neoplasm involving the stomach. "It was also shown that miR-145-5p affects gastric cancer progression via the ANGPT2/NLR axis and participates in angiogenesis, proliferation and migration of cancer cells." (PMID 41153678, 2025). "The expression of DARPP-32 and t-DARPP proteins plays an important role in promoting angiogenesis by regulating the expression and secretion of ANGPT2 in gastric cancer cells." (PMID 38308500, 2024). "The ANGPT2 and Tie2 axis plays a role in vascular remodeling and tumor progression, with NETs increasing ANGPT2 expression in gastric cancer models." (PMID 38474175, 2024). "So we have reason to think that ANGPT2 is involved in the regulation of immune microenvironment for gastric cancer." (PMID 36172371, 2022). "ANGPT2 has been reported to be involved in several kinds of cancer, but its role in peritoneal metastasis of gastric cancer is still not fully understood." (PMID 36503378, 2022). "We explored the crosstalk between gastric cancer and endothelial cells mediated by vesicles, with a specific focus on angiopoietin-2." (PMID 35740619, 2022). "Using angiopoietin-2 knockdown, we demonstrate that angiopoietin-2 mediates the proangiogenic effects of the gastric cancer vesicles." (PMID 35740619, 2022). "The low expression of ANGPT2 also affects the level of related proteins in this pathway, thus inhibiting the metastasis of gastric cancer cells." (PMID 34790582, 2021). "The discrepancies of angiogenic expression in tumor cells between angiopoietin-1 and angiopoietin-2 have been reported in multiple types of cancer, including oral cancer, gastric cancer, and colon cancer." (PMID 32799882, 2020). "The phase III AVAGAST trial provided evidence that angiopoietin-2 (Ang-2) serum levels in gastric carcinoma patients strongly correlate with hepatic metastases in particular." (PMID 32023907, 2020). "Newer biomarkers like angiopoietin-2 show promising results for targeted therapy in gastric cancers as well." (PMID 29568650, 2018). "For example, miR-218 suppresses gastric cancer cell proliferation via regulation of angiopoietin-2, and miR-218 inhibits proliferation of glioma cells by targeting ROBO1." (PMID 30157923, 2018). "In fact, DARPP-32 or t-DARPP positively regulates mRNA and protein expression and secretion of ANGPT2 in gastric cancer cells, thereby inducing angiogenesis." (PMID 26872373, 2016). "A recent report indicated that DARPP-32 promotes angiogenesis through regulation of angiopoietin 2 (ANGPT2) in gastric cancer." (PMID 26872373, 2016). "Production of angiopoietin-2 also contributes to tumor angiogenesis of gastric cancer in the presence of VEGF by induction of proteases in endothelial cells." (PMID 20369064, 2010). "Furthermore, we found high levels of ANGPT2 expression in the tumor tissues of gastric cancer patients and even greater levels in adjacent tissues using immunohistochemical staining; the results were statistically significant." (PMID 37480055, 2023). "We show that primary gastric cancer and omental metastasis tissues express angiopoietin-2." (PMID 35740619, 2022). "This study aimed to investigate the relationship among miR-145-5p, ANGPT2 and the NOD_LIKE_RECEPTOR pathway, thereby revealing the molecular mechanism of these three factors underlying the proliferation, migration and invasion of gastric cancer (GC) epithelial cells." (PMID 32874130, 2020). "The importance of FGF-2, PDGF-BB, and angiopoietin-2 for lymphatic metastasis of human gastric cancer is still unknown." (PMID 20369064, 2010). "Further studies revealed that NETs upregulated angiopoietin-2 (ANGPT2), and ANGPT2 was significantly correlated with macrophage M0, NK cell resting, and mast cell activation, suggesting that NETs might be involved in the regulation of the immune microenvironment in gastric cancer." (PMID 36993957, 2023).
gastric cancer (continued). "High concentrations of pro-angiogenic factors, such as VEGF, angiopoietin 2 (ANG2), and platelet-derived growth factor (PDGF), are present in the TME of various cancers, such as non-small cell lung cancer, gastric cancer, colorectal cancer, and glioma." (PMID 38193080, 2023). "More importantly, the positive correlation observed between MYBL1 and ANGPT2 expression was not only confirmed in a cohort of human HCC specimens, but also in several published datasets such as pancreatic cancer, gastric cancer, and stomach adenocarcinoma." (PMID 35987690, 2022). "Among these, the selection of 19 HERSRDEGs such as ANGPT2, ERG1, CD36, NOX4 and TLR2, provides critical insights into the potential roles these genes may play in gastric cancer pathophysiology." (PMID 40061897, 2025).
lung cancer (25 papers, 2016 to 2025). A malignant neoplasm involving the lung. "Hu and colleagues examined five ANGPT2 variants, rs2442598, rs734701, rs1823375, rs11137037, and rs12674822, and their impact on the development and course of lung cancer." (PMID 40115011, 2025). "Our recent study also demonstrated that the Angpt2 rs11137037 polymorphism was associated with a high risk of clinical-stage lung cancer in people of Han Chinese ethnicity." (PMID 31929743, 2020). "Interestingly, the association of Angiopoietin-2 levels with the type of surgical approach makes Angiopoietin-2 a valuable factor in selecting the most suitable therapeutic strategy for lung cancer patients." (PMID 34833409, 2021). "VEGFA is positively associated with ANGPT2 in lung cancer cell lines and tumor tissues of ADC." (PMID 31892982, 2020). "The results showed that HIF-1α mRNA expression was positively correlated with ANGPT2 both at lung cancer cell lines (r=0.513, P=0.007) and lung cancer tissues (r=0.285, P<0.001)." (PMID 31892982, 2020). "Meta-analyses of 22 gene expression omnibus (GEO) databases of lung cancer implicated that patients with higher VEGFA and ANGPT2 mRNA expressions tended to have advanced stage in ADC rather than SQC." (PMID 31892982, 2020). "Cobalt chloride (CoCl2) was adopted to mimic a hypoxic microenvironment and western blot was used to detect the expression of hypoxia inducible factor-1α (HIF-1α), VEGFA and ANGPT2 in lung cancer cell lines." (PMID 31892982, 2020). "The expression and clinical significance of VEGFA and ANGPT2 have been investigated in lung cancer, but the results are controversial." (PMID 31892982, 2020). "In the lung cancer vascular permeability increases upon upregulation of angiopoietin 2 (Angpt2), MMP3, and MMP10 in the pre-metastatic stage." (PMID 29720982, 2018). "ANGPT2 also proved to be a serum marker of poor prognosis in lung cancer." (PMID 34680307, 2021). "The clinical significance of VEGFA and ANGPT2 in lung cancer has been reported in previous studies." (PMID 31892982, 2020). "Finally, we demonstrated that simultaneous high expression of ADAM9/VEGFA or ADAM9/ANGPT2 are linked to poor prognosis, which shows the clinical relevance of ADAM9-mediated vascular remodeling in lung cancer progression." (PMID 29118335, 2017). "Plasma angiopoietin-2 levels in different stages of nonsmall cell lung cancer." (PMID 27512865, 2016). "In addition, studies have found that the expression level of ANGPT2 in serum might be a potential predictor in lung cancer staging and correlated with prognosis." (PMID 32874130, 2020). "Angiopoietin-2 (ANGPT2) is reportedly to facilitate angiogenesis, growth and metastasis in various cancers, including lung cancer." (PMID 36907878, 2023). "Although ADAM9 has been shown to enhance pulmonary vascular remodeling in lung cancer via VEGFA, angiopoietin-2, and tissue plasminogen activator, there is a paucity of literature linking ADAM9 to PH." (PMID 36522710, 2022). "Our results showed ADAM9 silence in lung cancer cells significantly reduce the VEGFA and ANGPT2 expression." (PMID 29118335, 2017). "We show that ADAM9 promotes vascular remodeling in lung cancer cells by increasing the expression of VEGFA, ANGPT2, and PLAT." (PMID 29118335, 2017). "The observation in animal models is consistent with the clinical dataset analyses that poor outcomes in lung cancer patients with simultaneous high expression of ADAM9 and VEGFA or of ADAM9 and ANGPT2." (PMID 29118335, 2017). "In this study, we demonstrate that VEGFA, ANGPT2, and PLAT are up-regulated in ADAM9-expressing lung cancer cells." (PMID 29118335, 2017). "Angiopoietin-2, an angiogenic regulator, promotes MCF7 cell survival through ILK-AKT1/2 signaling and dramatically decreases lung cancer patients' survival." (PMID 26967563, 2016).
glioma (22 papers, 2012 to 2025). A benign or malignant brain and spinal cord tumor that arises from glial cells (astrocytes, oligodendrocytes, ependymal cells). "We additionally analyzed the expression of a panel genes (Angpt2, Sox4, Vegfa, Kdr, Itga1, Mcam, Notch4 and Ets1) associated with vascular abnormality in ECs using RNA extracted from total glioma tumor tissues from control and treated mice." (PMID 34867089, 2021). "More specifically, IDHwt gliomas displayed a specific angiogenic gene expression signature (i.e., upregulation of Angiopoietin 2 and serpin family H) which resulted in enhanced endothelial cell migration and matrix remodeling." (PMID 35670981, 2022). "Enhanced expression of laminin subunit alpha 4 and angiopoietin 2 in WHO grade II glioma was confirmed by staining of human tumor tissue microarrays." (PMID 35670981, 2022). "Some intriguing aspects of the core gene set identified in this study include the well-studied glioma-related genes ANGPT2, CD44, SPP1, STAT3, PDGRFA, and TOP2A (all up-regulated), and BRSK1, DKK3, FGFR2, MAPK9, MEF2C, and PTEN (all down-regulated)." (PMID 29352201, 2018). "In contrast, genes encoding angiogenic factors (ANGPT1, ANGPT2) and receptors (NRP1, and KDR) were highly expressed in SA-culture-derived glioma cells of 51B." (PMID 29113349, 2017). "One mechanism may involve cooption of native blood vessels by glioma cells inducing expression of angiopoietin-2 by endothelial cells." (PMID 38960965, 2024). "Moreover, Angiopoietin-2 (Ang-2) increases the secretion of matrix metalloproteinase-2 (MMP-2) favoring human glioma cells invasive capacity." (PMID 35433447, 2022). "Although anti-VEGF (vascular endothelial growth factor) therapy with bevacizumab failed in GBM patients, its combination with angiopoietin-2 (Ang-2) inhibition led to M2-to-M1 reprogramming in the tumor microenvironment and prolonged survival in glioma-bearing mice." (PMID 31708781, 2019). "The proangiogenic compounds involved in the development of glioma include hypoxia-inducible factor 1α (HIF-1α), angiopoietin-2 (ANG-2), and interleukin-1β (IL-1β)." (PMID 40429943, 2025). "For example, BsAbs targeting angiopoietin-2 (Ang-2) and vascular endothelial growth factor (VEGF) have altered TAM activity in preclinical glioma models." (PMID 41272822, 2025). "Bispecific antibodies, targeting angiopoietin-2 (Ang-2) and vascular endothelial growth factor (VEGF), showed TAMs reprogramming and delayed tumor growth in glioma murine models." (PMID 33050070, 2020). "An angiogenic regulator, angiopoietin 2, induces invasion by stimulating MMP-2 expression and secretion in glioma cells." (PMID 23304519, 2012). "Moreover, activation of these pathways has been associated with increased expression levels of angiogenic factors, such as ANGPT2, COX2, and VEGFA, in glioma." (PMID 33718179, 2021). "In order to explore whether this contradiction exists in gliomas, we compared the expression levels of vascular stability-related markers (ANGPT1, ANGPT2, JAM2, MCAM, PDGFRB, and VE-Cadherin) in the high- and low-score glioma groups in the TCGA, CGGA, and CGGA (array) datasets." (PMID 35579998, 2022). "Inhibition of ANGPT2 and the subsequent activation of TIE-2 by the ANG2 Binding TIE-2 Activating Antibody (ABTAA) improves vascular stabilization and drug delivery in mouse models of orthotopic glioma, subcutaneous Lewis lung carcinoma and spontaneous mammary cancer." (PMID 31217905, 2019). "Moreover, when comparing TAGs from the mature GBM phenotypes to TAGs from non-angiogenic gliomas, we observed a significant upregulation of Vegf, Angiopoietin 2 and Fgf2." (PMID 28173797, 2017).
colorectal cancer (17 papers, 2010 to 2025). A primary or metastatic malignant neoplasm that affects the colon or rectum. "(2020) discovered a link between Angpt2 (rs12674822) single nucleotide polymorphisms (SNPs) and colorectal cancer patients’ progression-free survival (PFS)." (PMID 36845691, 2023). "Using RNA sequencing data obtained from OncoDB, ANGPT-2 (AUC = 90.8%) and VEGF-A (AUC = 95.1%) in COAD and VEGF-A in READ (AUC = 97.3%) had AUC > 90% and can be diagnostic factors for colorectal cancer." (PMID 38719941, 2024). "First, angiopoietin-2 expression was shown to be correlated with colorectal cancer stages and progression." (PMID 24373251, 2013). "Levels of the main angiogenic factors, vascular endothelial growth factor-A (VEGF-A) and angiopoietin-2 (Ang-2), are correlated with tumour progression and patient outcome in colorectal cancer." (PMID 21081932, 2011). "PHF20L1 promotes EMT of colorectal cancer cells and increases their invasiveness and metastatic abilities; it also regulates the expression of various angiogenic factors (such as ANGPT2, FGF1, PDGFA, and VEGFA) and promotes angiogenesis in colorectal cancer tissues." (PMID 40723918, 2025). "Prior studies have showed that plasma levels of angiopoietin-2 and VEGF were increased after surgical resection of primary tumors in the lung, breast, and colorectal cancer." (PMID 32799882, 2020). "Previous studies showed that surgical injury increases the plasma levels of angiopoietin-2 and VEGF in the lung, breast, and colorectal cancer." (PMID 32799882, 2020). "Investigators have showed surgical trauma stimulates the release of angiopoietin-2 and VEGF in plasma and promotes the process of angiogenesis in the lung, breast, and colorectal cancer." (PMID 32799882, 2020). "Our in vitro experiments revealed a novel mechanistic insight: MAGEA3 specifically inhibits the expression and secretion of VEGF through the mTOR signaling pathway in colorectal cancer cells, while exhibiting minimal impact on other key angiogenic factors such as PDGF, FGF, and ANGPT2." (PMID 40342736, 2025). "ANGPT-1, ANGPT-2, and VEGF-A expression in colorectal cancer datasets." (PMID 38719941, 2024). "Angiopoietin-2 (Ang-2), a relatively novel regulator of angiogenesis that acts through the TEK tyrosine kinase (Tie2) endothelial receptor, has been identified as a potential prognostic biomarker for some types of cancer, including HCC and breast, thyroid and colorectal cancers." (PMID 31991869, 2020). "The mean values of RQ for VEGF-A was discovered to be higher in patients with stage III/IV colorectal cancer (P-value = 0.001), but no statistically significant differential expression was identified between ANGPT-1 and ANGPT-2 expression and tumor stage." (PMID 38719941, 2024).